MET (MET proto-oncogene, receptor tyrosine kinase)
Diseases named in the same sentence as MET in open-access papers (continued):
Sharing a sentence is not in itself a finding about the gene and the disease.
breast carcinoma (continued). "Our observations do not provide a mechanistic understanding of the role of MET copy number alterations in predicting pCR in HER2-positive breast cancer." (PMID 27576528, 2016). "An immunogenotypic signature of low complexity comprising MET relative copy number and Ki-67 expression generated by dual ISH and IHC may help predict pCR in ERBB2-positive breast cancer treated with neoadjuvant chemotherapy and trastuzumab." (PMID 27576528, 2016). "The significance of MET amplification or deletion in the response to adjuvant or neoadjuvant therapy for ERBB2-positive breast cancer is not well established." (PMID 27576528, 2016). "In invasive and metastatic MTLn3 breast carcinoma cells, HGF stimulated both initial adhesion to and motility on the ECM ligands laminin 1, type I collagen, and fibronectin, and induced rapid tyrosine phosphorylation and activation of both c-MET and FAK." (PMID 28536400, 2015). "At present, however, there are no strong clinical data on the efficacy of MET inhibition in treating bone metastases from breast cancer." (PMID 24260160, 2013). "For breast cancer, there are additional cell surface target molecules: Mucin-1, EGFR, c-MET." (PMID 24351672, 2013). "Therefore the panel EGFR, MET, HER2, GLUT1, CAIX, and IGF1-R detected 84.2% of the basal/TN ductal breast cancers compared to 45.0% of the luminal-type, and 18.3% of the lobular breast cancer cases." (PMID 22695343, 2012). "In addition, the significant therapeutic effect of cabozantinib, which targets MET, VEGFR2, and AXL, for bone metastasis in patients with RCC, prostate cancer, and breast cancer also indicates the importance of MET inhibition in the treatment of bone metastasis." (PMID 40299443, 2025). "However, to the best of our knowledge, there are currently no published data demonstrating the effects of TAS-115 on c-MET/HGF interactions in breast cancer and metastasis." (PMID 41289612, 2025). "The expression of the MET/ESR genes could be a novel prognosticator and calls for future studies to evaluate the impact of combinational treatment approaches with MET inhibitors and endocrine drugs in breast cancer." (PMID 39742369, 2024). "Thus, the coexpression status of MET and ESR2 could predict a response to treatment in patients with breast cancer." (PMID 39742369, 2024). "In addition, molecular interactions between MET and ERBB receptor family signaling pathways may lead to resistance of breast cancer to HER2- and EGFR-targeted therapies, implying that MET is promising for the development of oncodriver-targeted therapies." (PMID 36900322, 2023). "Importantly, a fragment of the intracellular domain of HER2, termed 611-CTF (carboxy terminal fragment), can constitutively homodimerize and regulate MET, EPHA2, matrix metalloproteinase 1, interleukin 11, angiopoietin-like 4, and different integrins, promoting mammary tumor growth and metastasis." (PMID 37138747, 2023). "The specific binding of its target ligand EMI-137 was confirmed with in vitro studies, which showed cytoplasmatic accumulation of EMI-137 in the MET-positive PTC cell line (TPC1), whereas no EMI-137 binding was observed in the MET-negative breast cancer cell line (T-47D)." (PMID 35389070, 2022). "In particular, high ST8SIA1 expression was observed in patients with the basal-like breast cancer subtype (together with high MET oncogene expression), as well as in breast cancer stem cells (CSC), compared to non-CSCs, which exhibit lower motility and lower mammosphere formation." (PMID 35267607, 2022). "Beyond drugs that directly target proteins such as ER, EGFR, HER2, MET, PI3K, AKT, mTOR, and those of the MAPK pathway, anti-apoptotic protein inhibitors (BH3 mimetics) are now being evaluated as new targeted therapies for breast cancer as increased anti-apoptotic protein levels have been reported." (PMID 34359829, 2021).
breast carcinoma (continued). "In addition, unlike breast cancer, several aberrations are able to drive trastuzumab resistance in GC, including mutations in EGFR, MET, KRAS, PI3K, and PTEN genes, as well as EGFR, MET, and KRAS amplifications." (PMID 33916206, 2021). "In conclusion, we have identified that TGFβ1 regulates HGF‐induced and MET‐mediated cell migration, through positive regulation of C‐ets‐1 and negative regulation of miR‐128‐3p expression in basal‐like breast cancer cell lines and in triple‐negative breast cancer tissue." (PMID 30004628, 2018). "Moreover, in cancer development, their functional crosstalk has been reported with EGFR activating MET or, conversely, with MET expression regulating EGFR tyrosine phosphorylation and cell growth, e.g., in the presence of gefitinib (EGFR inhibitor) in SUM229 breast cancer cells." (PMID 30227653, 2018). "The hepatocyte growth factor receptor (MET) was among the top significant genes positively correlating with TGFBR2 expression, which could be validated using an independent dataset of breast cancer cell lines." (PMID 30004628, 2018). "In order to choose cancer cell lines that expressed high levels of both c-MET and EGFR, Western blot and real time polymerase chain reaction (PCR) analyses were performed using four cell lines: ovarian carcinomas SKOV3 and A2780, renal carcinoma A498, and breast carcinoma MCF7." (PMID 29291022, 2017). "Finally, several lung and breast cancer cases have been identified harboring MET exon 14 skipping detected by GEM ExTra tumor RNA sequencing, suggesting FDA-approved therapeutic options such as MET-inhibitors in these tumor types as recommended by NCCN (data not shown)." (PMID 33889297, 2021). "Hence, our finding that MACC1 overexpression is closely related to the clinical outcome of breast cancer warrants further and in-depth investigation on whether and how MACC1 interacts with the HGF-c-MET pathway, or other signaling pathways, in this highly prevalent malignancy." (PMID 23497677, 2013). "Our estimation of positivity of breast cancers for our panel may have been conservative since we have been very stringent in calling expression positive, explaining why our rates of expression for GLUT1, CAIX, EGFR, MET, TfR, CAXII, and Mammaglobin are on the lower side compared to the literature." (PMID 22695343, 2012). "TAS-115, a multi-target tyrosine kinase inhibitor of c-MET, VEGFR, and PDGFR, has shown antitumor efficacy in several malignancies but has not yet been evaluated in breast cancer." (PMID 41289612, 2025). "Unlike FOXC1 and MET, the functional role of ANLN in breast cancer has not been studied extensively." (PMID 33854062, 2021). "A significant positive correlation between PD-L1 and MET was also found in several cancer cell lines, including NSCLC, breast cancer, and sarcoma, but not in others, such as stomach cancer and lung small cell carcinoma." (PMID 31480591, 2019). "Unlike SKOV3 and A498, levels of c-MET and EGFR were not lowered by NRF2 knockdown in colorectal carcinoma HT29 and breast carcinoma MDA-MB231 cells." (PMID 29291022, 2017). "Expression of IGF1-R, MET, FGFR2, and CD44v6 was not correlated to clinicopathological features in both male and female breast cancer." (PMID 23308200, 2013). "COPG1 was not reported in TWAS or PWAS for breast cancer, but reducing the expression of the COPG1 gene lessened the accumulation of full-length nuclear c-MET, a receptor tyrosine kinase commonly overexpressed in various malignant cancers, including breast cancer." (PMID 39468330, 2024). "In contrast, in the low invasive/nonmetastatic breast cancer cell line T47D, which had no detectable MET and CDCP1 expression, ectopic MET expression stimulated the HGF-dependent activation of invasive activity, and concomitant CDCP1 expression activated SRC and further promoted invasive activity." (PMID 35085554, 2022).
breast carcinoma (continued). "Consequently, as the progression of the 4T1 cell line used in our study is not addicted to c-MET signaling, our data suggest that OMO-1 does not reduce in vivo 4T1 tumor progression solely by targeting the mammary tumor cells." (PMID 33731699, 2021). "We demonstrate that MET-T1010I has marked functional consequences in the MCF-10A normal breast epithelial cell line, which is more likely to reflect the appropriate context for breast cancer than previous studies with BA/F3 and NIH-3T3." (PMID 25605252, 2015). "However, five genes (CDC20, MET, KIF23, ANXA1, and CASP1) that are found in the TNBC group were not highly expressed in the HR+ breast cancer subtypes but are commonly found in the ER−/PR+ and ER−/PR− groups such that they could be used as negative controls." (PMID 39000600, 2024).
gastric cancer (428 papers, 2007 to 2026). A primary or metastatic malignant neoplasm involving the stomach. "For MET rs33917957, although the information for rs33917957 is limited, a previous study focused on gastric cancer has suggested that the MET N375S variant genotypes (NS/SS) were associated with a significantly decreased risk of gastric cancer." (PMID 39991569, 2025). "In a model-based analysis of response and resistance factors of cetuximab treatment in gastric cancer cell lines, the model predicted the effect of MET mutations on cetuximab sensitivity." (PMID 37046849, 2023). "In this review, we discuss how diagnostic testing of MET overexpression/amplification is performed in gastric cancer, and, next, provide an overview of all clinical studies that have been published with cMET inhibitors in gastric cancer." (PMID 37046637, 2023). "Although genetic mutations of MET gene have been detected in 1-2% of patients with gastroesophageal cancer, they are extremely rare in patients with gastric cancer overall." (PMID 35069735, 2022). "The antitumor effect of MET targeted therapy was investigated in human gastric cancer cells in vitro and in vivo, and the underlying molecular mechanisms were analyzed by western blot." (PMID 34557411, 2021). "Alterations in RTK activities, including EGFR, HER2 (ErbB2, EGFR2), and MET (HGFR), are associated with gastric cancer progression." (PMID 32005975, 2020). "High MET expression was associated with poor prognosis with statistical significance based on the gastric cancer tissue microarray." (PMID 34766112, 2020). "Overexpression of c-MET has been reported as associated with poor prognosis in patients with gastric cancer." (PMID 31395059, 2019). "The extreme susceptibility of MET amplification to the PHA-665752 has been experimentally confirmed in gastric cancer cell lines." (PMID 31265947, 2019). "Alternatively, it is possible that activating MET mutations act at an early stage in tumor progression and/or become less important in established human gastric cancer cell lines." (PMID 28881678, 2017). "In conclusion, this is the first study to evaluate the overexpression of MET as a risk factor for PD-L1 positivity in gastric cancer tissue as well as the reliability and prognostic relevance of PD-L1/MET co-expression after surgery." (PMID 29137273, 2017). "Other studies have similarly shown that MET gene amplification in gastric cancer is significantly associated with unfavorable clinical outcomes, including substantially shorter survival." (PMID 29108334, 2017). "Mesenchymal–epithelial transition factor (MET) is expressed in gastric cancer and associated with poor clinical outcomes." (PMID 29071414, 2017). "MET amplification has been clinically credentialed as a therapeutic target in gastric cancer, but the molecular mechanisms underlying sensitivity and resistance to MET inhibitors are still not well understood." (PMID 28881678, 2017). "Met-dependent loss of CBL protein in MET-amplified gastric cancer cell lines represents another mechanism contributing to signal dysregulation in gastric cancer." (PMID 27472394, 2016). "Aberrant HGF/MET axis activation has been implicated in the progression of multiple human tumor types, including liver, lung and gastric carcinomas, and results in cell survival and migration and tumor development and progression." (PMID 27013592, 2016). "Recent studies demonstrated MET overexpression and MET amplification were associated with poorer clinical outcomes in non-small cell lung cancer and gastric cancer." (PMID 25965822, 2015). "Patients selected by MET protein overexpression and MET amplification in gastroesophageal cancers, MET germline mutations in papillary renal cell cancer, and chromosome polyploidy in gastric cancer have been associated with response to MET inhibitors." (PMID 26155941, 2015). "In conclusion, our findings indicate that sf-RON signaling is implicated in the unresponsiveness of MET+ gastric cancer to MET inhibitors." (PMID 26528757, 2015).
gastric cancer (continued). "In gastric cancer, gain-of-function mutations of MET are exceedingly rare, with MET activation having been attributed mostly to gene amplification." (PMID 23327903, 2013). "In the present study, a polymorphism of c-MET gene (rs41739) was significantly associated with gastric cancer risk and a possible genetic susceptible factor on gastric cancer." (PMID 22383989, 2012). "Numerous previous studies reported that c-MET, one of the receptor TKs, promotes invasive tumor growth, cell invasion, and mortality, and amplification and/or overexpression of c-MET was associated with various human carcinoma including gastric cancer." (PMID 22383989, 2012). "Point mutations of MET were found in both hereditary and sporadic papillary renal cancer and gastric carcinoma, in childhood liver carcinoma, and lymph node metastases of head and neck squamous carcinoma." (PMID 22973229, 2012). "This study was undertaken to examine immunohistochemical expression of c-MET and its clinicopathological association in gastric carcinoma, by using tissue microarray (TMA) technology." (PMID 22640970, 2012). "It is important to note that in patients with advanced gastric cancer, co-expression of c-MET and HER2 has been associated with poorer survival compared to overexpression of either one." (PMID 20500904, 2010). "However, aberrant expression or activation of c-MET has been implicated in several malignancies such as breast, liver, lung, colorectal, and gastric cancers, making it an attractive target for therapeutic intervention." (PMID 39355533, 2024). "Furthermore, exosomes facilitate the transfer of molecules such as activated MET protein, instructing tumor-associated macrophages to enhance gastric cancer progression." (PMID 39726601, 2024). "This patient was enrolled on to a MET inhibitor (small molecule) trial, and as implicated in genomic alterations, his stomach cancer was responsive to the MET inhibitor, but his peritoneal seeding was rapidly deteriorating, which resulted in death from the disease." (PMID 38137393, 2023). "Overall, only MET‐amplified gastric cancer cells were susceptible to LY2801653 treatment." (PMID 34766112, 2020). "Lung adenocarcinoma cell lines, including H596 (harboring a MET exon 14 skipping mutation) and H1993 (harboring a MET amplification), and a gastric carcinoma cell line, Hs746T (harboring both a MET exon 14 skipping mutation and MET amplification), were used in this study." (PMID 31480591, 2019). "Here, we conducted targeted next generation sequencing (NGS) on the circulating tumor DNA (ctDNA) of a stage IV gastric cancer patient, and identified a reservoir of mutations that echoed the mutations found in a contemporaneous tissue biopsy including MET amplification." (PMID 28460431, 2017). "In this study, we focused on the aberrant co-overexpression of PD-L1 and MET in gastric cancers to determine whether this aberrant expression was associated with the clinical outcome." (PMID 29137273, 2017). "MET gene overexpression is related to a bad prognosis; it is associated with a more aggressive disease, a shorter OS, and disease free survival compared to MET-negative gastric cancers." (PMID 29094049, 2017). "PD-L1+/MET+ group would be a subtype associated with oncogenic PD-L1 signaling in gastric cancers." (PMID 29137273, 2017). "Similarly, gastric cancers are associated with the overexpression or amplification of other molecules such as MET, MSTIR, and FGFR2, and multiple trails testing the efficacy of inhibitors against these molecular mutations are also ongoing." (PMID 25025766, 2014). "Our observations thus indicate that gastric cancer cell lines positive for MET amplification depend predominantly on constitutive activation of the encoded growth factor receptor for their survival and thus show high sensitivity to cell killing by MET-TKIs." (PMID 23327903, 2013).